PDGFRB (platelet derived growth factor receptor beta)
Diseases named in the same sentence as PDGFRB in open-access papers (continued):
Sharing a sentence is not in itself a finding about the gene and the disease.
mesothelioma (10 papers, 2010 to 2025). A usually malignant and aggressive neoplasm of the mesothelium which is often associated with exposure to asbestos. "By inhibiting PDGFRβ signaling, other investigators decreased cell viability, increased apoptosis, and induced cell cycle arrest in mesothelioma." (PMID 34206917, 2021). "High PDGFRB expression in mesothelioma tumor cells is a negative prognostic marker, especially in patients with epithelioid histology." (PMID 33955203, 2021). "Kaplan–Meier OS analysis results show that PDGFRB revealed significant prognostic differences in GBMLGG, LGG, KIRP, KIPAN, STAD, SKCM-P, BLCA, Mesothelioma (MESO), Uveal Melanoma (UVM), PAAD, and LAML but not in ACC and KICH." (PMID 40128057, 2025).
renal carcinoma (10 papers, 2012 to 2025). A carcinoma arising from the epithelium of the renal parenchyma or the renal pelvis. "Analyzes how enhanced histone lactylation caused by inactive von Hippel-Lindau (VHL) may accelerate the development of renal cancer by activating the PDGFRβ signal." (PMID 39968078, 2025). "Nude mice with established renal carcinoma xenograft (No.213847) were treated with AL3810 for five consecutive days significantly reduced PDGFRβ positive cells in tumour tissue." (PMID 22304225, 2012).
triple-negative breast carcinoma (10 papers, 2018 to 2025). An invasive breast carcinoma which is negative for expression of estrogen receptor (ER), progesterone receptor (PR), and human epidermal growth factor receptor 2 (HER2). "Preclinical in vitro and in vivo models of triple-negative breast cancer provided further promising data regarding reduced tumor growth and metastasis in combinatorial treatment studies with the PDGFRβ-inhibiting aptamer and anti-PD-L1 antibodies." (PMID 38980580, 2024). "A nuclease-resistant RNA aptamer (Gint4.T) was recently described as a high-affinity inhibitor of PDGFRβ in mouse models of glioblastoma and metastatic triple-negative breast cancer, showing tumor-suppressive effects." (PMID 38980580, 2024). "Activation of PDGFRB/ERK pathway has been found to promote progression of triple-negative breast cancer." (PMID 33731124, 2021). "CDCP1 upregulation upon the activation of the PDGFRβ/ERK axis was confirmed in two additionally triple negative breast cancer cell lines BT-549 and SUM149." (PMID 29792166, 2018). "This approach may hold promise, particularly for triple-negative breast cancers, which frequently show elevated expression levels of both PD-L1 and stromal PDGFRβ." (PMID 38980580, 2024). "We first propose that combining PDGFRβ blockade with anti-PD-L1 immune checkpoint inhibitors may be a viable therapeutic approach for triple-negative breast cancer." (PMID 32892748, 2020). "Transcriptome sequencing analysis and in vitro studies showed that ezetimibe could significantly inhibit the expression of PDGFRβ and AKT in triple-negative breast cancer cells, suggesting that ezetimibe may enhance the therapeutic effect of antitumor drugs by inhibiting the PDGFRβ/AKT pathway." (PMID 38027998, 2023).
Cirrhosis (9 papers, 2011 to 2025). A chronic disorder of the liver in which liver tissue becomes scarred and is partially replaced by regenerative nodules and fibrotic tissue resulting in loss of liver function. "Interestingly, although the elevated tissue-expression of PDGFRβ upon fibrosis/cirrhosis and HCC, its expression was found to be down-regulated in the circulation of HCC patients, as compared to cirrhotic controls." (PMID 34362181, 2021). "Thus, selective PDGFRβ drug targeting allows the delivery of compounds to inhibit ROCK-mediated HSC contraction during cirrhosis, as shown by the decreased hepatic p-moesin and p-MLC in Y27pPBHSA-treated rats." (PMID 30783172, 2019). "Since in cirrhosis, platelet-derived growth factor receptor beta (PDGFRβ) is upregulated in the liver as well as the kidney, this study coupled Y27 to human serum albumin (HSA) substituted with PDGFRβ-recognizing peptides (pPB), and investigated its effect on PTH in cirrhotic rats." (PMID 30783172, 2019). "80–90% of human HCC arise in the setting of a cirrhotic liver, in which HSCs have been activated, so we first performed IHC analysis to determine whether PDGFRα and PDGFRβ levels are elevated in human cirrhosis and HCC." (PMID 24667490, 2014). "Platelet-derived growth factor receptor beta (PDGFRβ), the receptor of PDGF-BB, is a key mediator of liver injury and fibrogenesis in vivo and contributes to the poor prognosis of HCV-related cirrhosis." (PMID 39781468, 2025). "The present study shows that ROCK inhibition targeted to PDGFRβ might be a promising strategy to treat PHT in cirrhosis without adverse extrahepatic hemodynamic effects." (PMID 30783172, 2019).
cognitive decline (9 papers, 2019 to 2026). "Recent evidence shows that elevated baseline CSF PDGFRβ is associated with increased hippocampal Ktrans and predicts future cognitive decline in APOE ε4 carriers." (PMID 40145342, 2025). "Recently, the Zlokovic group has successfully connected the BBB-associated pericyte injury biomarker, soluble PDGFRβ, in cerebrospinal fluid (CSF) to cognitive decline in apolipoprotein E (APOE4) carriers even after controlling for Aβ and tau status." (PMID 34630020, 2021). "DISCUSSION: This study demonstrated that decreased plasma PDGFRβ levels are associated with BBB damage, Aβ plaques, tau tangles, neurodegeneration, and cognitive decline in AD, and modulate the relationship between plasma tau biomarkers and both longitudinal neurodegeneration and cognitive decline." (PMID 41530860, 2026). "CSF PDGFRβ levels at the MCI stage could be capturing the specific contribution of pericyte damage to cognitive decline progression." (PMID 40239464, 2025). "While pericyte loss leading to elevated PDGFRβ may initially be an age‐related process, the resulting damage to the BBB is associated with an increased risk of cognitive decline, especially in patients at the highest risk of ADRD." (PMID 40145342, 2025). "Furthermore, elevated PDGFRβ in the CSF was shown to predict cognitive decline in APOE4 carriers." (PMID 33132896, 2020). "To summarize, this study identifies early and progressive pericyte loss, compromised PDGFRβ expression, and vascular Aβ accumulation in postmortem retina of MCI and AD patients along with their significant correlation to cerebral pathology and cognitive decline." (PMID 32043162, 2020). "Recently, mutations in four different genes (SLC20A2, PDGFRB, PDGFB, and XPR1) were identified, together with novel mutations in the Myogenic Regulating Glycosylase gene, causing the occurrence of movement disorders, cognitive decline, and psychiatric symptoms." (PMID 31267306, 2019). "In a subset of patients with neuropathological reports, retinal vascular PDGFRβ expression significantly correlated with CAA and cognitive decline assessed by the Mini-Mental State Examination (MMSE)." (PMID 34630020, 2021). "However, it remains unclear whether plasma platelet-derived growth factor receptor-β (PDGFRβ) level is related to BBB damage and how it correlates with AD core pathologies, neurodegeneration, and cognitive decline." (PMID 41530860, 2026).
COVID-19 (9 papers, 2021 to 2025). A disease caused by infection with severe acute respiratory syndrome coronavirus 2. "Notably, cerebrospinal fluid from additional 16 individuals (n = 8 COVID-19, median age = 67 years; n = 8 control, median age = 69.5 years) exhibited significantly lower levels of the pericyte marker PDGFRβ in SARS-CoV-2-infected cases, indicative of disrupted pericyte homeostasis." (PMID 34769052, 2021). "While our mIHC of brain tissue demonstrated a surprisingly variable occurrence of PDGFRβ+ perivascular cells, in line with the results from the CSF analysis, the analysis did not support an overall diminished pericyte coverage of the vasculature of COVID-19 patients." (PMID 34769052, 2021). "By 6 weeks post-inclusion, COVID-19 hypermethylation of genes with the highest fold-change compared to healthy controls included FAM178B, FYN, TMCC1, TMEM212-AS1, and FIG4, while the top five hypomethylated genes were GIT2, PDGFRB, SEMA6D, TNFAIP8, and ETV6." (PMID 41227320, 2025). "Further, DTP-based retrieval of approved drugs showed that combination therapy with sorafenib, sunitinib, nintedanib (PDGFRB), sunitinib, nintedanib, ruxolitinib (JAK1), and ceritinib (IGF1R) could be helpful to diabetic COVID-19 patients." (PMID 34067609, 2021).
dementia (9 papers, 2020 to 2026). Loss of intellectual abilities interfering with an individual's social and occupational functions. "Notably, the association with PDGFRβ was significantly higher for CSF GFAP levels in the dementia group (β = 0.141 [CI95% 0.055–0.228], P = 0.0020)." (PMID 40239464, 2025). "We aimed to test whether CSF PDGFRβ was associated with different AD-associated and age-associated pathologic changes leading to dementia." (PMID 37137722, 2023). "Higher PDGFRβ levels were associated with lower cognitive performance, both in MCI and dementia groups." (PMID 40239464, 2025). "We observed a weak correlation of CSF PDGFRβ with the CSF/plasma albumin quotient, considered a biomarker of blood-CSF barrier integrity, driven by the dementia group, as it has already been reported." (PMID 40239464, 2025). "Investigating separately MCI and dementia stages, CSF PDGFRβ levels were only significantly higher in the N+ individuals compared to N- at the MCI stage with a medium effect size (Cohen's d = 0.50 [CI95% 0.040–0.97], P = 0.031, Supp." (PMID 40239464, 2025). "Higher CSF PDGFRβ levels were associated with lower MMSE scores at MCI (β = −1.23 [CI95% −2.33, −0.260], P = 0.015) and dementia stages (β = −2.24 [CI95% −3.62, −0.85], P = 0.0020)." (PMID 40239464, 2025). "Late-life SBP correlated negatively with frontal WM PDGFRB in dementia cases (r = −0.1821, P = 0.0413) but not controls (ns) and not in the parietal WM in either group (both ns)." (PMID 37113314, 2023). "QAlb was also consistently associated with PDGFRβ in CU and MCI and at whole cohort level, with the exception of the dementia subgroup." (PMID 37137722, 2023). "The relation of CSF PDGFRβ with markers of amyloid pathology, neuroinflammation, and axonal and synaptic damage across dementia remains unclear." (PMID 40239464, 2025). "Platelet-derived growth factor receptor β (PDGFRβ) is expressed in the brain mainly in brain capillary pericytes and levels of soluble PDGFRβ (sPDGFRβ) could be used as a biomarker of pericyte injury, as elevated sPDGFRβ levels in biofluids have been measured in patients with dementia." (PMID 36012569, 2022). "Notably, other related genes, such as “PDGFRB,” “MYORG,” “XPR1,” and “JAM2,” as well as phenotypic traits like “dementia” and “parkinsonism,” also exhibited significant node sizes." (PMID 40456615, 2025). "In the frontal and parietal WM, PDGFRB did not correlate with DBP in controls or dementia cases (all ns)." (PMID 37113314, 2023). "Late-life SBP correlated negatively with PC PDGFRB in controls (r = −0.2290, P = 0.0219) but not dementia cases (ns)." (PMID 37113314, 2023). "In the FC and PC, PDGFRB did not correlate with DBP in either controls or dementia cases (all ns)." (PMID 37113314, 2023). "Late-life SBP did not correlate with FC PDGFRB in either controls or dementia cases (both ns)." (PMID 37113314, 2023). "CSF PDGFRβ did not significantly differ between MCI and dementia groups." (PMID 40239464, 2025).
lymphoma (9 papers, 2012 to 2025). A malignant (clonal) proliferation of B- lymphocytes or T- lymphocytes which involves the lymph nodes, bone marrow and/or extranodal sites. "Additional eight mutations that were significantly enriched in rHL/prHL affect genes that were previously associated with the progression of other lymphoma subtypes (e.g., PDGFRB, KAT6A, HGF, EPHB1, NSD2, PMS2)." (PMID 39992429, 2025). "It has been reported that imatinib, a tyrosine kinase inhibitor of PDGFRβ, induced apoptosis of tumour-associated PDGFRβ1 pericytes and impaired growth of lymphoma, indicating that pericytes may represent a novel target for lymphoma therapy." (PMID 36226068, 2022). "One study showed impaired growth of lymphoma in both human xenograft and mouse allograft models with the use of imatinib, a tyrosine kinase inhibitor of PDGFRB." (PMID 30101129, 2018). "As a result, the case in the present article is the first case report of lymphoma and concurrent AML bearing PDGFRB gene mutations." (PMID 22356850, 2012). "Our findings, which are supported by two independent lymphoma patient datasets, propose PDGFRβ is yet another potent kinase in the list of regulators of IL-10 expression in ALCL and that targeting the PDGFRβ/STAT5/IL-10 axis is an attractive therapeutic strategy." (PMID 36045346, 2022). "PDGFRB rearranged cells are known to develop into B and T lineage lymphoma." (PMID 22356850, 2012). "Inhibition of platelet derived growth factor receptor B (PDGFRB) with imatinib mesylate or sunitinib malate has shown some efficacy in carcinoma models but has not yet been thoroughly evaluated in the context of lymphomas." (PMID 30101129, 2018).
schizophrenia (9 papers, 2011 to 2025). A major psychotic disorder characterized by abnormalities in the perception or expression of reality. "Besides the association with NK cell functions via PDGFRB, a number of studies reported that the downregulation of the PI3K/Akt pathway is associated with autism spectrum disorder and schizophrenia." (PMID 37872602, 2023). "Among the 7 DEGs, the TNC gene was the only gene that decreased with schizophrenia and showed a positive correlation with PI (16:0/20:4), while the other 6 DEGs (COL1A2, COL6A2, DDIT4, FGF17, GNB3, and PDGFRB) increased with schizophrenia and showed a negative correlation with PI (16:0 /20:4)." (PMID 37143779, 2023).
bladder cancer (8 papers, 2010 to 2025). "Together, it is reasonable to assume that PDGFRB is an important receptor for bladder cancer biological progression, and it should serve as a potential biomarker for NMIBC diagnosis and/or prognosis." (PMID 24801713, 2014). "It was further observed that EGF and CDH1 in the PPI network were annotated as being bladder cancer-associated proteins, and both receptor FGFR2 and PDGFRB could interact with EGF." (PMID 24801713, 2014). "We developed a Risk Score model that was related to the overall survival of bladder cancer patients based on doxorubicin-target HRGs: ACTG2, MYC, PDGFRB, DHRS2, and KLRD1." (PMID 38806990, 2025). "Because PDGFRB/EGFR heterodimers were reported to express on bladder cancer cells, and the EGF/EGFR pathway played an important role in bladder cancer development, PDGFRB was selected for further validation as a candidate biomarker of bladder cancer." (PMID 24801713, 2014). "Moreover, PDGFRB rather than FGFR2 could form a heterodimer with EGFR on bladder cancer cells, and this could induce resistance to anti-EGFR therapy for bladder cancer." (PMID 24801713, 2014).
endometrial cancer (8 papers, 2013 to 2025). Primary or metastatic malignant neoplasm involving the endometrium (mucous membrane that lines the endometrial cavity). "In endometrial cancer (EC), circCHD7, a circular RNA upregulated in tumor tissues, interacts with IMP2 to stabilize the mRNA of platelet-derived growth factor receptor beta (PDGFRB)." (PMID 40141058, 2025).
epilepsy (8 papers, 2018 to 2026). A brain disorder characterized by episodes of abnormally increased neuronal discharge resulting in transient episodes of sensory or motor neurological dysfunction, or psychic dysfunction. "Further supporting this, our proteomics data revealed downregulation of ITRRIP and PDGFRB, both of which play roles in calcium signaling and have been associated with epilepsy." (PMID 41597222, 2026). "PDGFRβ was proposed as a possible pharmacological target in epilepsy and the PDGFRβ agonist PDGF-BB reduced mural cell loss, vascular pathology, and epileptiform activity." (PMID 38338969, 2024). "In addition, within the regional scar that is a hallmark of epilepsy, a fibrotic-like PDGFRβ mesh was shown to develop around the capillaries, peaking at early stages post-SE, and regressing, but not resolving during the SRSs." (PMID 38338969, 2024). "The decreased expression of PDGFRβ from PILO 14D to PILO 3M may be due to the loss of mural pericytes known to occur in epilepsy." (PMID 38338969, 2024). "In addition, the amount of angiogenesis, which is associated with epileptogenesis, was related to the number of PDGFRβ-positive cells, suggesting a relationship between PDGFRβ-positive cells and the pathogenesis of epilepsy." (PMID 34209145, 2021). "PDGFRβ can regulate pericyte survival, proliferation, and migration signals and is commonly used as a marker for pericytes; PDGFRβ suppression has been proposed as a possible treatment for epilepsy." (PMID 34209145, 2021). "Epilepsy-related proteins, including upregulation of GRM1 and COMT and downregulation of PDGFRB and OTX2, were noted." (PMID 41597222, 2026). "In the present work we investigated, during the different phases of epilepsy, in the rat hippocampus, the regulation of the neuroinflammatory GFAP and Iba1 markers and vascular proteins of the BBB, such as CD31, PDGFRβ, and ColIV." (PMID 38338969, 2024). "The findings from both in vitro and in vivo studies highlight the potential of pericytes as a therapeutic target for seizure disorders, as indicated by the efficacy of PDGF-BB and imatinib in blocking PDGFRβ." (PMID 34209145, 2021).
Fahr disease (8 papers, 2015 to 2025). "Background and Aims: Mutations in PDGFRB are linked to Primary Familial Brain Calcification (PFBC), a neurodegenerative disorder marked by basal ganglia calcifications." (PMID 40542608, 2025). "Recently, heterozygous PDGFRB mutations have been described in patients diagnosed with idiopathic basal ganglia calcification (IBGC or Fahr disease), a rare inherited neurological disorder." (PMID 25292412, 2015). "Finally, heterozygous loss-of-function variants of PDGFRB, among other genes, have been associated with primary familial brain calcification (also named idiopathic basal ganglia calcification 4 or Fahr disease, OMIM 615007)." (PMID 32888134, 2021). "The gene PDGFRB has been confirmed as causative of primary familial brain calcifications (PFBC)." (PMID 28558704, 2017). "Mutations in PDGFRβ and its ligand, PDGFB, are linked to the genetic disorder idiopathic basal ganglia calcification (IBGC)." (PMID 34082828, 2021). "Genes implicated in Fahr's disease include PDGFB, PDGFRB, SLC20A2, XPR1, MYORG, and JAM2." (PMID 37780723, 2023).
ischemia (8 papers, 2016 to 2024). A hypoperfusion of the BLOOD through an organ or tissue caused by a PATHOLOGIC CONSTRICTION or obstruction of its BLOOD VESSELS, or an absence of BLOOD CIRCULATION. "After integration of the batches, 1,425 cells passed the quality assessment, of which 148 and 737 were tdTomato+PDGFRβ+ from the healthy and ischemic muscles (day 21 after ischemia), respectively, whereas 177 and 363 were tdTomato−PDGFRβ+." (PMID 39196227, 2024). "Pericyte-specific activation of PDGFRβ in response to either ischemia or traumatic brain injury has been shown in rodent models to be important in wound healing." (PMID 27654972, 2016). "Interestingly, although the numbers of PDGFRβ− lineage-traced macrophages were similar before ischemia and at later stages of ischemia onset, PDGFRβ+ lineage-traced macrophages accumulated in ischemic hindlimbs." (PMID 39196227, 2024). "Elevated CSF sPDGFRβ likely reflects release of a soluble fragment of pericyte PDGFRβ, due to its cleavage by ADAM-10, as was shown in vitro in response to simulated ischemia or Aβ peptide." (PMID 31521199, 2019). "These ischemia/injury-induced multipotent stem cells (iSCs) expressed not only pericytic markers (e.g., PDGFRβ, neural/glial antigen 2 (NG2), and alpha-smooth muscle actin (αSMA)), but also various stem cell markers (e.g., nestin, c-myc, Klf4, and Sox2)." (PMID 32887241, 2020).